ITPA (inosine triphosphatase)
Description:
Pyrophosphatase that hydrolyzes the non-canonical purine nucleotides inosine triphosphate (ITP), deoxyinosine triphosphate (dITP) as well as 2'-deoxy-N-6-hydroxylaminopurine triphosphate (dHAPTP) and xanthosine 5'-triphosphate (XTP) to their respective monophosphate derivatives. The enzyme does not distinguish between the deoxy- and ribose forms. Probably excludes non-canonical purines from RNA and DNA precursor pools, thus preventing their incorporation into RNA and DNA and avoiding chromosomal lesions.
Synonyms: ITPase; NTPase; C20orf37; My049; HLC14-06-P; dJ794I6.3; DEE35
Tractability: Small molecule: a structure with a bound ligand is known; it has a high-quality binding pocket. PROTAC: ubiquitination databases record sites on it; its protein half-life has been measured.
Target class: Enzyme; Hydrolase
Safety:
Unwanted effects reported when the protein is acted on. In parentheses: how it was acted on, where the effect was seen, and who reports it.
adverse events (source: ClinPGx)
anemia (source: ClinPGx)
event free survival (source: ClinPGx)
gastrointestinal toxicities (source: ClinPGx)
leukopenia and neutropenia (source: ClinPGx)
myelosuppression (source: ClinPGx)
response to folic acid and methotrexate (source: ClinPGx)
Gene: Protein-coding gene on chromosome 20 (3,208,868 to 3,223,870, forward strand). Ensembl gene ENSG00000125877.
Subcellular location: Cytoplasm
Subcellular location (Human Protein Atlas): Cytosol; Nucleoplasm
Pathways (Reactome):
Drug ADME: Ribavirin ADME
Metabolism: Purine catabolism
Gene Ontology:
Molecular function: dITP diphosphatase activity; identical protein binding; ITP diphosphatase activity; XTP diphosphatase activity; nucleoside triphosphate diphosphatase activity
Biological process: purine nucleoside triphosphate catabolic process; deoxyribonucleoside triphosphate catabolic process; nucleoside triphosphate catabolic process
Cellular component: cytoplasm; cytosol; nucleoplasm; nucleus
Genetic constraint (gnomAD): Loss-of-function variants: 29 observed, 34.1 expected, observed/expected ratio (o/e) 0.85, 90% interval 0.63 to 1.16. The upper end of that interval is the gene's LOEUF score, 1.16, which puts it in group 5 of 6, group 1 being the genes least tolerant of losing a copy. Missense variants: 241 observed, 264.45 expected, observed/expected ratio (o/e) 0.91, 90% interval 0.82 to 1.01. Synonymous variants: 103 observed, 105.04 expected, observed/expected ratio (o/e) 0.98, 90% interval 0.83 to 1.15.
Gene-disease validity (ClinGen):
ClinGen rates the evidence that ITPA causes each of these diseases.
genetic developmental and epileptic encephalopathy (autosomal recessive): Definitive. A complex neurodevelopmental disorder characterized by a range of developmental delays and epileptic encephalopathy phenotypes.
Homologues: Orthologues: chimpanzee ITPA (99% identical), guinea pig ITPA (92% identical), rabbit ITPA (92% identical), pig ITPA (91% identical), mouse Itpa (90% identical), tropical clawed frog itpa (75% identical), rat Itpa (73% identical), zebrafish itpa (72% identical), Drosophila melanogaster CG8891 (63% identical), Caenorhabditis elegans hap-1 (57% identical), macaque ITPA (56% identical).
Diseases named in the same sentence as ITPA in open-access papers:
ITPA is named in the same sentence as 56 diseases in open-access papers, as found by Europe PMC text mining. Sharing a sentence is not in itself a finding about the gene and the disease. The quoted sentences say what the papers report.
anemia (25 papers, 2010 to 2025). A reduction in the number of red blood cells, the amount of hemoglobin, and/or the volume of packed red blood cells. "In HCV patients several ITPA gene single nucleotide polymorphisms (SNPs) have been reported to predict anemia while on therapy." (PMID 38468199, 2024). "Pretreatment characteristics including patient age, baseline hemoglobin, and ITPA rs1127354-CC genotype were independently associated with the development of anemia." (PMID 38468199, 2024). "Several reasons, including patient ITPA genotype, have been reported to be significantly associated with ribavirin-induced anemia during treatment." (PMID 38468199, 2024). "A study conducted in Peshawar Pakistan also reported that ITPA rs1127354 minor allele-A is protective against ribavirin-induced anemia during interferon ribavirin anti-HCV treatment." (PMID 38468199, 2024). "The results of present study determine that ribavirin based DAA therapy has good SVR achievement rate in our population and pretreatment evaluation of ITPA polymorphism can help to reduce the risk of developing anemia due to ribavirin." (PMID 38468199, 2024). "Pretreatment evaluation of ITPA polymorphism can be a diagnostic tool to find out patients at risk of anemia and improve treatment adherence." (PMID 38468199, 2024). "Japanese studies reported a correlation of ribavirin associated anemia incidence and ITPA SNP rs1127354 polymorphism and ribavirin dose reduction but was not linked to antiviral therapy outcome and no polymorphism of gene at ITPA SNP rs7270101was observed." (PMID 38468199, 2024). "The literature lacks studies of Pakistani population exploring the effect of ITPA polymorphism as a predicting factor for anemia development in HCV patients taking sofosbuvir ribavirin combination therapy." (PMID 38468199, 2024). "Studies on individuals of European, African, and Japanese population has shown an association between ITPA variants with ribavirin-induced anemia." (PMID 38468199, 2024). "In particular, polymorphisms near to the inosine triphosphatase (ITPA) gene locus are predictive of anemia resulting from RBV treatment." (PMID 36077436, 2022). "The ITPase lowering ITPA polymorphisms were shown to be protective against ribavirin-induced anaemia in hepatitis C on treatment." (PMID 29329318, 2018). "A total of 13 references were examined to evaluate the association between ITPA polymorphisms and severe anemia." (PMID 26438033, 2015). "Recently, it was shown that ITPA polymorphisms were also associated with anemia during IFN-free therapy." (PMID 26441325, 2015). "Although limited data is available, previous studies among patients treated with triple therapy including telaprevir also showed that a ITPA polymorphism (rs1127354) was associated with the development of on-treatment anemia." (PMID 26441325, 2015). "Genetic variation in the inosine triphosphatase (ITPA) gene on chromosome 20 is associated with the development of anemia during peginterferon and ribavirin therapy." (PMID 26650626, 2015). "Although most of the studies have been performed in patients on combined therapy (pegIFNα/RBV), a strong association between an ITPA SNP and anemia has been reported in patients on RBV monotherapy." (PMID 26438033, 2015). "Host IL28B genotype is known to be a strong predictor of response to interferon-based therapy, while patients with variants in the ITPA gene are known to be protected against ribavirin-induced anemia during treatment with peginterferon-containing regimens." (PMID 26650626, 2015). "Genetic variants in the ITPA gene protected against RBV treatment-induced anemia among Caucasian patients with chronic HCV infection." (PMID 26441325, 2015). "Our finding of a strong association between ITPA genotypes and the development of anemia is consistent with the results of earlier studies." (PMID 26650626, 2015).
anemia (continued). "The role of ITPA polymorphisms on early Hb decline and/or early anemia was identified by GWAS and further replicated in different ethnic groups treated both by PegIFN/RBV, and by a triple combination therapy with TVR." (PMID 26670100, 2015). "Only one of the 103 patients with anemia (hemoglobin <10 g/dL or decreased from baseline by ≥3.5 g/dL) had the ITPA-deficient AA or AC genotype at rs1127354." (PMID 26650626, 2015). "In most of the studies, the odds of developing anemia was more than double in patients with an unfavorable ITPA genotype than in patients with a protective ITPA minor variant." (PMID 26438033, 2015). "The ITPA rs6051702 C minor allele, a more common variant, has also been associated with protection from anemia." (PMID 26438033, 2015). "The combination of the two ITPA SNPs, rs1127354 and rs7270101, determines the relative deficiency of the ITPA protein, which in turn has been associated with the grade of anemia during PR therapy." (PMID 24760000, 2014). "Grade 3–4 anemia developed in 81% of non ITPA deficient versus 67% of mild ITPA deficient patients and 55% of moderate ITPA deficient patients (p = 0.1)." (PMID 24760000, 2014). "Inosine triphosphatase (ITPA) genetic variants are associated with RBV- induced anemia and dose reduction." (PMID 24760000, 2014). "For this reason we decided to study the role of single nucleotide polymorphisms (SNPs) in the Inosine Triphosphatase (ITPA) gene in determining PR+TVR early anemia in patients with HCV-1 advanced fibrosis/cirrhosis." (PMID 24760000, 2014). "Premature discontinuation for severe anemia occurred in 8% of non ITPA deficient patients (4/48), 8% of mild deficient patients (1/12) and 0% of moderate deficient patients (p = 1)." (PMID 24760000, 2014). "In theory this findings fit well with the loss of protection from ITPA deficiency towards on treatment anemia that we observed following 4 weeks of PR+TVR therapy." (PMID 24760000, 2014). "The Cochran-Armitage trend test indicated an effect of ITPA rs1127354 C allele carriers on Hb reduction at week 4 and only marginally at week 12, with the minor allele A ameliorating anemia (p = 0.005 and p = 0.056, respectively)." (PMID 25227310, 2014). "ITPA deficiency is thought to protect against Rbv induced anemia, by protecting against ATP depletion in the erythrocyte." (PMID 24760000, 2014). "Ribavirin is a purine analogue and previous studies have shown that ITPA genetic variants leading to ITPA deficiency are associated with ribavirin-induced anemia in HCV-treated patients." (PMID 23133602, 2012). "recently clarified that ITPA genetic variant protected anemia by accumulated inosine triphosphates been used for decreased ATP via adnylosuccsinate synthase." (PMID 23145809, 2012). "More recently, ITPA polymorphisms have been associated with a protective effect against ribavirin induced anaemia in patients with hepatitis C." (PMID 22272297, 2012). "Third, genetic variations that resulted in a deficiency in the enzyme inosine triphosphatase (ITPA) were recently found to protect HCV patients against ribavirin-induced anemia." (PMID 21304937, 2011). "Pretreatment determination of ITPA polymorphism will help in early identification of anemia predisposition and its associated complications, which may have various implications for HCV affected individuals." (PMID 38468199, 2024). "Missense variants are easier to be determined as causal variants by functional analyses or experiments, such as rs1127354 and rs7270101 in ITPA, which can predict the ribavirin-induced anemia, and rs3731249 in this study, which induce loss of function of the tumor suppressor p16INK4A." (PMID 29654170, 2018). "Therefore, currently ribavirin levels seem to be of little value to predict anemia, for which hopefully studies e.g. on polymorphisms in the inosine triphosphatase (ITPA) or the SLC28A2 genes will enable a more precise view in the future." (PMID 27388623, 2016).
anemia (continued). "Thus, ITPA polymorphisms will still be useful in preventing anemia while RBV continues to be included in HCV treatment regimens." (PMID 26438033, 2015). "Whether inosine triphosphatase (ITPA) gene polymorphisms predict anemia during interferon-free therapy in chronic hepatitis C virus (HCV)-infected patients is unknown." (PMID 26650626, 2015). "It has been reported that inosine triphosphatase (ITPA) gene variants protect against ribavirin-induced anemia in patients treated for chronic hepatitis C. IL28B variants also influence the treatment response of peginterferon plus ribavirin treatment in these patients." (PMID 23012624, 2012). "However, since our HIV+ cohort was relatively small it seems premature to draw a final conclusion about the relationship between ITPA polymorphisms and anaemia in HIV+ patients using antiretroviral therapy." (PMID 22272297, 2012). "So far, it remains unclear what impact an ITPA variant phenotype has on ribavirin-induced anaemia." (PMID 40581807, 2025). "Above, I have outlined examples where ITPA polymorphism/mutation is detrimental to patient outcomes (thiopurine toxicity/infantile death) and examples indicating that ITPA polymorphism is beneficial to patient outcomes (reduced anemia in hepatitis C patients, young-onset TB)." (PMID 27770805, 2016). "Although it is hard to explain why ITPA deficiency protects from development of anemia only in the early weeks of PR+TVR treatment, this might be the direct consequence of the increased plasma Rbv levels that have been reported to occur after 4 weeks of treatment with TVR." (PMID 24760000, 2014). "As ITPA deficiency causes the accumulation of ITP, which can be used to synthesize ATP, the ITPA 94C>A variant reduces the incidence of RBV-induced anemia." (PMID 35455413, 2022). "The effect of ITPA genotype on RBV-induced anemia has been shown in several studies both within IFN-containing and IFN-free regimens." (PMID 29851985, 2018). "Drug toxicity occurs in patients with ITPA variation undergoing thiopurine therapy, whereas development of anemia in the treatment of hepatitis C is delayed for individuals with ITPA polymorphism." (PMID 27770805, 2016). "Our results suggest that ITPA genotypes can predict anemia during treatment with interferon-free, ribavirin-containing regimens." (PMID 26650626, 2015). "We tested the association of IL28B and APOH SNPs with sustained virological response and of ITPA SNPs with anemia related phenotypes by means of logistic regression assuming an additive genetic model." (PMID 26670100, 2015). "There are currently no reports in the peer-reviewed literature on the effects of ITPA SNPs on ribavirin-induced anemia during interferon-free therapy." (PMID 26650626, 2015). "In this study, the unique CUPIC cohort of well characterized treatment experienced cirrhotic patients allowed us refining the association between IL28B SNPs and SVR to triple therapy, and between ITPA SNPs and anemia." (PMID 26670100, 2015). "ITPA rs1127354 major type led to significantly greater ribavirin-induced anemia than ITPA rs1127354 minor type in Japanese patients during peginterferon plus ribavirin treatment." (PMID 23012624, 2012). "ITPA rs1127354 is useful for the prediction of ribavirin-induced anemia in the early phase after the commencement of peginterferon plus ribavirin treatment and IL28B rs8099917 is useful for the prediction of sustained virological response." (PMID 23012624, 2012). "We should examine the relationships between ITPA gene variants and RBV-induced anemia in Japanese populations, and evaluate the usefulness as an index to reduce the risk of anemia with erythrocyte RBV level." (PMID 21151503, 2010). "Polymorphisms of Inosine triphosphatase (ITPA) gene may cause functional impairment in the Inosine triphosphate pyrophosphatase enzyme, resulting in enhanced sustained viral response (SVR) and protection from ribavirin-associated anemia in patients on therapy." (PMID 38468199, 2024).
anemia (continued). "The results of this study suggest that ITPA SNPs may help predict anemia in chronic hepatitis C patients treated with interferon-free regimens that contain ribavirin." (PMID 26650626, 2015). "We found that the ITPA-non-deficient genotypes rs1127354 CC and rs6051702 AA were associated with the development of anemia during treatment with faldaprevir, deleobuvir, and ribavirin in the SOUND-C2 study." (PMID 26650626, 2015). "The ITPA rs1127354 CC and rs6051702 AA genotypes may predict ribavirin-induced anemia during treatment with interferon-free, ribavirin-containing regimens." (PMID 26650626, 2015). "The ITPA rs1127354 CC genotype and absent ITPase deficiency haplotype were also associated with severe anemia {[OR = 7.77 (95 % CI 5.03; 12.00)] and [OR = 4.79 (95 % CI 1.69; 13.56)], respectively}." (PMID 26438033, 2015). "Since treatment response has been reported to be associated with ribavirin dose and/or anemia, we also explored predictors of SVR12, taking into account ITPA genotypes at both the rs1127354 and the rs6051702 positions, baseline hemoglobin levels, and on-treatment ribavirin concentrations." (PMID 26650626, 2015). "For the clinician, determining the presence of ITPA SNPs may help predict the development of anemia during chronic HCV treatment." (PMID 26650626, 2015). "Because reduced ITPase activity results in improved outcomes for patients undergoing ribavirin treatment, it is plausible that competitive ITPase inhibitors could be developed to help reduce anemia in individuals not affected by ITPA polymorphism." (PMID 27770805, 2016). "This may seem surprising since we found a strong association between both ITPA-non-deficient genotypes and anemia." (PMID 26650626, 2015). "This may reflect the fact that effective levels of ribavirin were also achieved in patients without anemia, who were most likely protected by ITPA-deficient genotypes." (PMID 26650626, 2015). "However the clinical utility of ITPA SNPs in predicting anemia severity in TVR based regimens to date is still relatively unknown, as it has been studied mostly in patients of Asian ethnicity and never in patients with advanced fibrosis/cirrhosis." (PMID 24760000, 2014). "Whatever the precise mechanisms by which ITPA deficiency fails to protect from PR+TVR severe anemia may be, our study shows that estimated ITPA deficiency grade through genotyping of rs1127354 and rs7270101 at baseline is of limited clinical utility." (PMID 24760000, 2014). "Thus, experiments that determine how variations in the ITPA level both in the absence and in the presence of ribavirin influence RBC lifespan would provide the necessary inputs for our model to account explicitly for the role of ITPA in ribavirin-induced anemia." (PMID 21304937, 2011). "Our study demonstrates that genetics of ITPA and IL28B may help identify patients protected from RBV-induced anemia when treated with IFN-free regimens." (PMID 29851985, 2018). "In patients with F3–F4 chronic hepatitis C receiving TVR based therapy, ITPA genotype does not impact on the management of early anemia." (PMID 24760000, 2014). "Next, we examined ribavirin-induced anemia among patients according to IL28B and ITPA genotypes." (PMID 23012624, 2012). "IL28B rs8099917 did not influence ribavirin-induced anemia, nor did ITPA rs6051702." (PMID 23012624, 2012). "Splenectomy improved SVR rate among patients carrying IL28B minor genotype and protected against anemia and thrombocytopenia during the course of PEG-IFN/RBV therapy regardless of ITPA genotype." (PMID 23145809, 2012).
acute lymphoblastic leukemia (10 papers, 2012 to 2023). Leukemia with an acute onset, characterized by the presence of lymphoblasts in the bone marrow and the peripheral blood. "We have recently demonstrated that TPMT and ITPA genotypes constitute a multilocus genotype of pharmacogenetic relevance for children with acute lymphoblastic leukemia (ALL) receiving thiopurine therapy." (PMID 23335936, 2012).